PYCR1 (pyrroline-5-carboxylate reductase 1)
Diseases named in the same sentence as PYCR1 in open-access papers (continued):
Sharing a sentence is not in itself a finding about the gene and the disease.
cancer (continued). "Single-factor Cox regression analysis revealed that PYCR1 was a high-risk gene for overall survival (OS) and progression-free survival (PFS) in eight cancer types." (PMID 39125668, 2024). "This is consistent with previous studies reporting elevated expression of PYCR1 in cancers such as LIHC, BLCA, and KIRP, which can predict unfavorable prognosis outcomes." (PMID 39125668, 2024). "Increased expression of P5CS and PYCR1 is a poor prognostic factor for different types of cancers, which suggests that cancer cells require proline biosynthesis." (PMID 39051546, 2024). "Our analysis highlighted the dysregulation of both MYO1B and PYCR1 in different cancer types, especially in the HNSC dataset." (PMID 39768999, 2024). "The biological consequences indicated that PYCR1 affected key hallmarks of cancer, including cell proliferation, anti-apoptosis, and metastasis." (PMID 39768999, 2024). "In agreement with previous studies, it was indicated that PYCR1 was the most frequently overexpressed metabolic gene across pan-cancer." (PMID 39768999, 2024). "Among the PYCR isoforms, PYCR1 has been studied the most extensively for its role in carcinogenesis, including in cancers of the kidney, lung, and prostate." (PMID 37508547, 2023). "There is increased expression of key metabolic enzymes (Arg1, OAT and PYCR1) in fibrotic tissue and cancer." (PMID 37752116, 2023). "Using RNA-seq analysis in TNBCs following PYCR1 depletion, cGMP-PKG signaling pathway responsible for promoting malignancy in numerous cancer types, is identified as a novel downstream target of PYCR1." (PMID 37845207, 2023). "Mechanistically, PYCR1-synthesized proline activates cGMP-PKG signaling to enhance cancer stem-like traits." (PMID 37845207, 2023). "Collectively, these data establish that PYCR1 promotes cancer stem-like traits and breast malignancy." (PMID 37845207, 2023). "Consistent with previous studies on PYCR1 in other cancers, our findings predicted that PYCR1 was overexpressed in ccRCC tissues, which indicated a poor prognosis for ccRCC patients." (PMID 37340189, 2023). "Pycr1 responds to the cell protection against oxidative stress 56 and mediates proline metabolism to support cancer cell proliferation and survival." (PMID 37284449, 2023). "In this study, we report the crucial role and the novel mechanism of proline metabolism regulated by PYCR1 in cancer stem-like cell maintenance, especially under psychological stress." (PMID 37845207, 2023). "Further investigation confirms that PYCR1-synthesized proline activates cGMP-PKG signaling pathway to enhance cancer stemness." (PMID 37845207, 2023). "Analysis of two commercially available TMAs containing both normal and CRC tissues confirmed accumulation of PYCR1 enzyme in cancer tissue." (PMID 35130302, 2022). "This is the first comprehensive meta-analysis about the influence of increased PYCR1 expression on the survival and clinicopathological characteristics of cancer." (PMID 36119513, 2022). "Our findings provided clues for understanding the clinicopathological significance of PYCR1 expression in cancer and are of great value for guiding new targets for cancer therapy." (PMID 36119513, 2022). "PYCR1 expression sustains cancer cells’ proliferation and survival and several mechanisms have been implicated to explain its oncogenic role." (PMID 35130302, 2022). "As an enzyme in proline metabolism, PYCR1 has a trend of increased expression in various cancers, which has been recognized by more and more researchers." (PMID 36119513, 2022). "The treatment of PYCR1 inhibited CAFs with proline or soluble collagen I rescued the proliferation of cancer cells in coculture with the CAFs." (PMID 35760868, 2022). "Second, some studies in vitro focused on the relationship between PYCR1 and cancer proliferation and migration." (PMID 36119513, 2022).
cancer (continued). "Compared with that in normal tissues, the expression of PRODH and PRODH2 was decreased in various cancer tissues, while that of P4HA and PYCR1 was increased in various cancer tissues." (PMID 36088469, 2022). "While exogenous proline can be obtained from the TME, de novo proline synthesis in cancer cells is required to maintain cellular redox state via NADH recycling by 5-carboxylate reductase 1 (PYCR1)." (PMID 36582801, 2022). "A study about the mRNA profiles of 19 types of cancers found that the expression of many metabolic genes was altered when compared with that in normal controls, and PYCR1 is one of the most frequently overexpressed metabolic genes." (PMID 36119513, 2022). "As one of the enzyme types, PYCR1 takes part in the whole process of the growth, invasion, and drug resistance of cancer cells." (PMID 36119513, 2022). "This study investigated PYCR1 expressions in cancers together with their relationship to clinical prognosis." (PMID 36119513, 2022). "It has been reported that, compared with normal tissues, PYCR1 gene expression was consistently higher in cancer tissues, and knockdown of PYCR1 impaired cancer cell proliferation." (PMID 36119513, 2022). "PYCR1 in cancer cells in conjunction with the mitochondria protease Lon elicits ROS-dependent production of pro-inflammatory cytokines that promote M2 macrophage polarization and angiogenesis." (PMID 36582801, 2022). "In some studies, high expression levels of PYCR1 have been recorded in multiple cancers, including HCC, breast cancer, and lung cancer, promoting the development and progression of tumors and is contrary to the overall survival rate." (PMID 35293266, 2022). "There is evidence that PYCR1 plays a pivotal function in the occurrence and advancement of human cancer, including liver." (PMID 35293266, 2022). "Guo and colleagues showed that extracellular matrix stiffening stimulated K2 translocation to mitochondria and its interaction with pyrroline-5-carboxylate reductase 1 (PYCR1) leads to enhanced proline synthesis supporting cancer cell proliferation." (PMID 35936112, 2021). "The linkage of proline metabolism is not limited to cancer but is also evident in viral proliferation as seen in the hijacking of proline biosynthetic enzymes (PYCR1) by Kaposi’s sarcoma herpes virus K1 and MYC-dependent adenoviral proliferation." (PMID 34825974, 2021). "Of note, our work reveals the abnormal PYCR1 expression in BLCA tissue as a consequence of FTO-induced m6A RNA demethylation, providing the potential mechanism accounting for the dysregulation of PYCR1 in other types of human cancer as well." (PMID 33461172, 2021). "Increased collagen matrix synthesis stiffens ECM, which in turn promotes kindlin-2 mitochondrial translocation and interaction with PYCR1, resulting in further up-regulation of PYCR1 level and proline synthesis in cancer." (PMID 33554046, 2020). "The importance of kindlin-2 mitochondrial translocation and interaction with PYCR1 in regulation of proline synthesis and cancer progression begs the question of what signaling proteins regulate kindlin-2 mitochondrial translocation and interaction with PYCR1." (PMID 33554046, 2020). "PYCR1 protein level was significantly higher than normal in the cancer samples pre‐treatment (P = 0.002), and despite some reduction upon treatment, it was still significantly higher than normal also in the post‐treatment samples (P = 0.047)." (PMID 32960509, 2020). "Although any interaction between PYCR1 and DJ-1 in cancer is yet to be established, these data warrant further investigation into their possible cooperation in promoting tumorigenesis by conferring protection to oxidative stress." (PMID 33083024, 2020). "In cancer cells, Lon expression triggers mitochondrial ROS production and, surprisingly, this depends on Lon interaction with PYCR1." (PMID 33083024, 2020).
cancer (continued). "The role played by PYCRs-mediated Proline synthesis in cancer progression is supported by unbiased transcriptomics, metabolomics, and proteomics studies, indicating that PYCRs expression levels, especially PYCR1, influence the clinical course of cancer." (PMID 32500033, 2020). "When ECM stiffness rises, as in cancer, Kindlin-2 translocates in the mithocondria where it interacts with PYCR1, increasing PYCR1 and proline levels." (PMID 32500033, 2020). "These phenotypic changes were associated with elevated intracellular proline abundance, when either PYCR1 was silenced or cancer cells were treated with the PRODH inhibitor THFA." (PMID 33109600, 2020). "Many cancers alter their proline metabolism by up-regulating the proline cycle and proline biosynthesis, and knockdowns of PYCR1 lead to decreased cell proliferation." (PMID 33109600, 2020). "An important role for PYCR1 in cancer is also suggested by numerous studies showing that it is one of the most consistently overexpressed metabolic enzymes across cancer types." (PMID 33109600, 2020). "Whilst it is generally acknowledged that PYCR1 plays a major role in cancer progression, some preliminary data suggest a pro-tumorigenic role for the PYCR2 gene as well." (PMID 33083024, 2020). "Consistent with an important role of proline synthesis in cancer progression, PYCR1 is one of the most frequently overexpressed metabolic enzymes in cancer." (PMID 33554046, 2020). "More recently, a meta-analysis covering 1981 tumors from 19 different types of cancers highlighted that PYCR1 is one of the most commonly overexpressed metabolic genes in human cancer." (PMID 33083024, 2020). "Kaplan–Meier analysis using Cox proportional hazard model showed that indeed patients with high PYCR1 level in post‐treatment residual carcinoma had poorer prognosis than patients with low PYCR1 level." (PMID 32960509, 2020). "Studies have shown that PYCR1 is abnormally expressed in a variety of malignant tumors." (PMID 41975648, 2026). "FA might reduce cancer development through various mechanisms, including modifying the cancer cell cycle, causing apoptosis, cell cycle blockade, and JAK/STAT, NF-κB, PYCR1, PI3K/AKT pathways." (PMID 40487371, 2025). "They found that removing PYCR1 reduced cancer cell growth and spread." (PMID 41254241, 2025). "Patient 58 carried a likely pathogenic variant in PYCR1; however, this patient did not have substantial information on pathological features or family history of cancer but was diagnosed at a relatively younger age (of 27 years)." (PMID 40627234, 2025). "Further review of work in the literature examined the role of PYCR1 in different types of cancer." (PMID 39768999, 2024). "PYCR1 is a cancer cell vulnerability and a potential target for therapy." (PMID 39335478, 2024). "High levels of proline and NADH, coupled with high PYCR1 expression, indicated higher proline biosynthesis, which might support cancer cell proliferation and survival in oxygen-limiting conditions." (PMID 38703764, 2024). "Based on pan-cancer analysis, PYCR1 was consistently expressed across various cancer types." (PMID 39768999, 2024). "Thus PYCR1 overexpression is related to the progression of several cancers, and reducing PYCR1 level can reduce tumorigenicity, providing a new idea for the precise treatment of diseases." (PMID 39312378, 2024). "Notably, the genes MYO1B and PYCR1 were significantly upregulated in various cancer types, especially the HNSC dataset, when compared to normal tissues." (PMID 39768999, 2024). "Future studies could delve deeper into the precise mechanisms by which PYCR1 and its metabolic products, such as lactate, regulate gene expression and cancer cell behaviour." (PMID 39422696, 2024). "Indeed, our results ensure that inhibition of PYCR1 dramatically reverses glutamine-induced proline production and cancer stemness." (PMID 37845207, 2023).
cancer (continued). "As high metastatic capacity and oncogenicity are major characteristics of CSCs, whether and how PYCR1-enhanced proline controls cancer stem-like properties remain to be determined." (PMID 37845207, 2023). "We further identified whether proline mediates PYCR1-induced stem-like properties and cancer progression." (PMID 37845207, 2023). "So far, it is not known whether proline metabolism is increased in hypoxia, despite the fact that some studies have revealed the potential of PYCR1 as a promising target in cancer therapy." (PMID 35105345, 2022). "The high expression of PYCR1 is associated with poor prognosis in most cancer patients, suggesting that PYCR1 may be a potential target for cancer therapy." (PMID 36119513, 2022). "Overexpression of PYCR1 is involved in progression of several cancers, however, its’ role in hematological cancers is unknown." (PMID 35105345, 2022). "Conversely, inhibiting PYCR1 in cancer cells in monoculture only modestly reduced proliferation." (PMID 35760868, 2022). "The higher the PYCR1 expression was, the poorer the cancer prognosis was." (PMID 36119513, 2022). "However, no meta-analysis has been performed to evaluate the prognostic value of a high expression of PYCR1 in cancer patients up to now." (PMID 36119513, 2022). "Mechanistically, PYCR1 expression sustains survival and proliferation of cancer cells." (PMID 35130302, 2022). "Current studies have shown that PYCR1 is involved in the process of cancer resistance." (PMID 36119513, 2022). "Hence, we have revealed a potentially important role of PYCR1 in CAFs to support cancer cell growth by supporting enhanced collagen production." (PMID 35760868, 2022). "In recent years, the impact of PYCR1 in many cancers cannot be ignored or underestimated." (PMID 35293266, 2022). "Therefore, in order to explore the clinical prognostic value of PYCR1 in various cancers, we conducted a meta-analysis of clinical studies on PYCR1 and cancer, aiming to provide more reliable evidence for basic research and clinical work." (PMID 36119513, 2022). "These suggested that PYCR1 expression did reflect the prognosis of many cancers." (PMID 36119513, 2022). "PYCR1 is a cancer cell vulnerability and potential target for therapy; therefore, our work provides evidence that targeting PYCR1 may have the additional benefit of halting the production of a pro-tumorigenic extracellular matrix." (PMID 35760868, 2022). "As a result, high expression of PYCR1 was induced in these cancer cells." (PMID 33465163, 2021). "Interestingly, overexpression of PYCR1 has been shown in many cancer types and has even been suggested to be directly pro-tumorigenic." (PMID 34291343, 2021). "Accumulating evidence has shown that PYCR1 exerts tumorigenic effects in a variety of cancers." (PMID 34696668, 2021). "Finally, recent findings showed a correlation between cancer cells that have mutation in isocitrate dehydrogenase 1 (IDH1) and increased PYCR1 expression and Proline levels." (PMID 32500033, 2020). "In these cancers, PYCR1 activity provides L-proline necessary for protein biosynthesis." (PMID 33083024, 2020). "This suggested that the cancer cells may be addicted to high levels of PYCR1 to sustain cell growth and provide oxidative stress resistance for cell survival." (PMID 31143549, 2019). "However, despite the compensatory increase of PYCR1 expression, the level of proline is often inadequate for maintaining high level of protein synthesis in proliferating cancer cells." (PMID 30783087, 2019). "Furthermore, a recent large-scale comparative analysis of published mRNA microarray datasets found that PYCR1 was one of the most commonly overexpressed metabolic enzyme genes in comparison to normal tissue among the 19 represented cancer types." (PMID 25621173, 2015). "Moreover, elucidating the broader molecular interactions of PYCR1 across different oncogenic contexts may reveal its role in other cancer types." (PMID 41254241, 2025).
cancer (continued). "PYCR1 gene expression could predict poor cancer characteristics and patient outcomes." (PMID 36119513, 2022). "In addition, there is little data about the change of PYCR1 expression in cancer management." (PMID 36119513, 2022). "We explored whether SK performed an anti-tumoral effect via suppressing PYCR1 in live cancer cells." (PMID 35293266, 2022). "Third, PYCR1 could also induce cancer progression by enhancing cell migration and invasion ability." (PMID 36119513, 2022). "In addition, we noticed that PYCR1 has been reported to be a significant cancer driver and its silencing could significantly suppress carcinogenesis and progression." (PMID 34696668, 2021). "Intuitively, PYCR1 activity might satisfy cancer cells’ increased demand for the NEAA L-proline." (PMID 33083024, 2020). "Thus, evidence is growing for PYCR1 as a potential cancer therapy target." (PMID 33109600, 2020). "Furthermore, because of the antioxidant capacity of proline, overexpression of PYCR1 and increased proline biosynthesis may contribute to enhanced cancer cell survival." (PMID 33109600, 2020). "This could also be extended to other cancers where PYCR1 is known to be upregulated." (PMID 32960509, 2020). "Thus, the proline cycle enzymes PRODH and PYCR1 are emerging cancer therapy targets." (PMID 33109600, 2020). "In addition to its involvement in cancer, PYCR1 could also be involved in other disease related processes." (PMID 31428683, 2019). "High expression of Pyrroline-5-Carboxylate Reductase-1 (PYCR1), along with elevated levels of proline and NADH, suggests increased proline biosynthesis in high wGII tumors, potentially supporting cancer cell proliferation and survival under hypoxic conditions." (PMID 41035074, 2025). "PYCR1 interacts with EGFR, activating the PI3K–AKT pathway to enhance aerobic glycolysis and support cancer cell proliferation in bladder cancer." (PMID 41254241, 2025). "After analysing various LC cell lines in the Cancer Cell Line Encyclopedia (CCLE) database, we observed a negative correlation between the methylation level and the expression level of PYCR1." (PMID 39422696, 2024). "The expression of PYCR1 was positively correlated with TMB in 18 cancer types and positively correlated with MSI in 9 cancer types, while it was negatively correlated with MSI in READ." (PMID 39125668, 2024). "Ablation of PYCR1 markedly reverses psychological stress-induced proline synthesis, cGMP-PKG signaling activation and cancer progression." (PMID 37845207, 2023). "Ablation of PYCR1 reverses psychological stress-induced cGMP-PKG signaling activation, stem-like traits and cancer progression." (PMID 37845207, 2023). "Dysregulation of pyrroline-5-carboxylate reductase 1 (PYCR1) and microRNA hsa-miR-150-5p is involved in the development of various cancers." (PMID 34696668, 2021). "ECM stiffness characteristic for cancer ECM induces kindlin-2 translocation into mitochondria where it interacts with PYCR1, increasing PYCR1 activity and subsequently proline level." (PMID 34769188, 2021). "Specially, bta-miR-34c and bta-miR-449b potentially regulated PYCR1 and DDIT4, which were involved in cancer progression and angiogenesis." (PMID 31772843, 2019). "An important role of MYC in this process was previously reported in human cancer cell lines, where MYC inhibits PRODH and promotes the transcription of PYCR1 and ALDH18A1." (PMID 29132502, 2017). "Mitochondrial PYCR1 and PYCR2 are upregulated in multiple types of cancer, including prostate, lymphoma, and others." (PMID 25621173, 2015). "The GSEA revealed that cancer-related gene modules were remarkably enriched in patients with upregulated TLR4, TLR2, TLR1 and PYCR1 (TLR4upTLR2upTLR1upPYCR1up) compared with patients with a downregulated expression of these markers (TLR4downTLR2downTLR1downPYCR1down)." (PMID 41254241, 2025).